POSTN (periostin)
Diseases named in the same sentence as POSTN in open-access papers (continued):
Sharing a sentence is not in itself a finding about the gene and the disease.
asthma (continued). "Furthermore, in the neutrophilic asthma phenotype, periostin expression in the nasal cavity was lower than in healthy controls and in the eosinophilic phenotype." (PMID 34439751, 2021). "Likewise, in the present study, an aggravation of AR in patients with asthma was accompanied by a significant accumulation of periostin in nasal secretions; p=0.048." (PMID 34796003, 2021). "The POSTN gene is upregulated in asthmatic airway epithelium by Th2 cytokines and can be used as a biomarker for long-term predictability in the management of severe asthma." (PMID 34566492, 2021). "When inhaled corticosteroids (ICS) are administered to asthma patients, periostin production is reduced, suggesting that airway inflammation is suppressed, and serum periostin levels have been demonstrated to decrease in response to systemic therapy and ICS therapy." (PMID 34439751, 2021). "Periostin, a matricellular protein produced by airway epithelial cells under the control of IL-4 and IL-13, is a key molecule linking TType2/eosinophilic airway inflammation and remodeling in asthma." (PMID 32824775, 2020). "Finally, four patients had comorbid asthma, and they exhibited numerically higher serum periostin level, compared with that in the remaining subjects." (PMID 32517742, 2020). "Periostin, a 90-kD extracellular protein which is mainly produced by fibroblasts in response to interleukin (IL)-4 and IL-13, is a notable biomarker which reflects the pathophysiology of both asthma and CRS." (PMID 32015784, 2020). "Additionally, we noted that 7/12 (58%) patients with asthma had a relatively high level of IS periostin together with sputum eosinophilia and a relatively high level of IS TSLP." (PMID 33203095, 2020). "In addition to collagen Iα1, IL-1α/β, but not IL-33, also suppressed the expression of the ECM proteins, periostin and fibronectin, which are known to be altered in expression in asthma." (PMID 32457454, 2020). "Both the six gene signature (6GS: CPA3, DNASE1L3, CLC, IL1B, ALPL, and CXCR2) and T‐helper 2 signature (TH2S: CLCA1, SERPINB2, and POSTN) are proposed as biomarkers in the identification of inflammatory phenotypes of asthma in induced sputum and epithelial brushings, respectively." (PMID 31903716, 2020). "To date, levels of only periostin or only TSLP have been studied in asthma and COPD patients." (PMID 33203095, 2020). "Besides asthma, periostin is also involved in other diseases, such as atopic dermatitis, allergic rhinitis, and chronic rhinosinusitis." (PMID 33203095, 2020). "Compared with cluster 3, cluster 4 showed a high serum periostin level (87.1 ± 32.3 vs. 66.5 ± 21.8 ng/mL, p = 0.05) and a higher prevalence of the comorbidities: DM (p < 0.01), albuminuria (p < 0.01), hypertension (p = 0.03), and asthma (p = 0.01)." (PMID 32517742, 2020). "These indicate that periostin in the lower airways may be further produced through activated eosinophils under an inflammatory situation like asthma." (PMID 32015784, 2020). "Because OSA is a well-known comorbidity in obese patients with asthma and contributes to poor asthma control, serum periostin may assist in the management of this treatable trait in refractory asthma." (PMID 32517742, 2020). "Periostin is induced by IL-13 and has been studied as a biomarker of asthma." (PMID 30937129, 2019). "However, that systematic review included asthma patients in different severity from mild to severe, and it didn’t assess the possibility of periostin level as biomarker for anti-IL-13 treatments." (PMID 30703143, 2019). "In two replicate studies (LUTE and VERSE) in patients with moderate-to-severe uncontrolled asthma, lebrikizumab (37.5, 125 or 250 mg s.c. every 4 weeks) reduced asthma exacerbation rate by 60% compared to placebo in periostin-high patients and by 5% in periostin-low patients." (PMID 31866859, 2019). "Notably, a high serum concentration of periostin denotes one of the most significant indicators of eosinophilic inflammation in asthma." (PMID 31590215, 2019).
asthma (continued). "The role of periostin in asthma and type 2 inflammatory responses has been increasingly recognized." (PMID 30308057, 2018). "Moreover, periostin has emerged as a novel biomarker for asthma, reflecting type 2 inflammation and tissue remodeling in asthma patients." (PMID 29642409, 2018). "However, the present study also showed an inverse correlation between serum periostin and asthma disease severity, i.e., patients with mild to moderate asthma had high serum periostin levels." (PMID 30473714, 2018). "Since periostin is associated with Th2 driven inflammation and inhaled corticosteroid (ICS)-response in asthma, it could function as a biomarker in COPD." (PMID 29879994, 2018). "It has been described, together with POSTN and chloride channel accessory 1, as a gene-signature for Th2 asthma and mainly IL-13 asthma phenotype, but until our knowledge, SERPINB2 protein expression has only been studied in broncoalveolar lavage (BAL) and never before at a peripheral level." (PMID 29977241, 2018). "Higher cutoff point of serum POSTN in CRSwNP than asthma might reflect local inflammation in nasal polyps." (PMID 30061580, 2018). "Patients with EGPA had significantly higher periostin levels when compared to previously published cohorts of healthy controls (mean periostin 66 ng/ml [SD 25] vs 51 ng/ml [SD 12], p < 0.01) and patients with asthma (mean periostin 66 ng/ml [SD 25] vs 51 ng/ml [SD 14], p < 0.01)." (PMID 30308057, 2018). "In asthma, serum periostin may potentially be used as a biomarker in the management of patients with Type-2 eosinophilic airway inflammation." (PMID 30065761, 2018). "Notably, while the periostin levels were fairly stable across visits, they were overall much higher than previously-described cohorts, including patients with asthma, despite the concurrent use of immunosuppressive therapy." (PMID 30308057, 2018). "It seems that periostin is involved in inflammatory process of asthma, with levels decreasing with corticosteroids and it could be useful for monitoring disease progression." (PMID 28815006, 2017). "Therefore, we investigated the associations between the previously analyzed parameters of a prothrombotic state in asthma and concentrations of IL-6 and TNFα and periostin in peripheral venous blood." (PMID 28429138, 2017). "In addition to blood eosinophil counts there are other biomarkers of type 2 diseases, such as serum periostin and fractional exhaled nitric oxide (FeNO), which are being investigated in asthma." (PMID 29034234, 2017). "Recently serum periostin, a matricellular protein generated by airway epithelial cells and partly regulated by IL-13, has been proposed as a biomarker with a potential clinical role in severe asthma." (PMID 28194189, 2017). "The observation that CS markedly reduces IL‐13‐induced CLCA1 and POSTN expression, which does not recover after CS cessation, is an important finding for biomarker‐guided therapy in asthma since especially periostin is considered as an emerging biomarker for Th2 inflammation." (PMID 28701525, 2017). "Periostin and vascular cell adhesion protein 1 (VCAM-1), molecules that mediate leukocyte infiltration and are associated with inflammatory disorders involving marked eosinophilia (e.g. asthma), were particularly elevated in the peritoneum." (PMID 28584245, 2017). "The improvement of asthma symptoms by clarithromycin may be attributed to the downregulation of these genes in addition to periostin." (PMID 28219384, 2017). "The clinical trials of the LAVOLTA studies, which were designed to assess the rate of severe asthma exacerbations over 52 weeks in a group with high serum periostin concentrations, enrolled and treated 2148 patients from 28 countries in the northern and southern hemispheres." (PMID 29155876, 2017). "Further studies are needed on the role of periostin as an asthma biomarker in childhood asthma." (PMID 28815006, 2017).
asthma (continued). "As macrolides also affect type 2-dominated inflammation in asthma, we hypothesized that macrolide therapy may attenuate IL-13 stimulated periostin production and inflammatory gene expression in human lung fibroblasts." (PMID 28219384, 2017). "In a post hoc analysis of the asthma group, there was a change in classification from ‘high periostin’ to ‘low periostin’, based on the 0800 and 1800 h periostin levels, utilizing the proposed cut point of 50 ng/mL in 1/16 participants (50.3 and 48.2 ng/mL at 0800 and 1800 h, respectively)." (PMID 28194189, 2017). "Besides this allergic phenotype the “Th2-high asthma” is characterized by increased levels of Type 2 inflammation in the airways including eosinophilia and overexpression of periostin." (PMID 27942351, 2016). "Periostin proteins in peripheral blood correlate with airway eosinophilic inflammation, and have therefore the potential to be used as a biomarker to select patients for asthma therapies targeting TH2 inflammation." (PMID 27965769, 2016). "In addition, asthma exacerbations were substantially reduced in the periostin-high subgroup (30 %) relative to placebo." (PMID 26993628, 2016). "Similarly, patients with high levels of exhaled nitric oxide (NO), blood eosinophils, or serum periostin, had fewer asthma exacerbations following treatment with omalizumab, a neutralizing anti-IgE antibody, than patients with low biomarker levels." (PMID 26993628, 2016). "Biologicals targeting the Th2-eosinophil nexus such as anti–interleukin (IL)-4, anti–IL-5, and anti–IL-13 are ineffective in asthma as a whole but are more effective if patients are selected using cellular (eg, eosinophils) or molecular (eg, periostin) biomarkers." (PMID 26334389, 2016). "There are limited studies supporting the utility of periostin in the management of asthma." (PMID 27130294, 2016). "To further elucidate the immunopathological mechanism(s) mediating inflammation in childhood asthma, we investigated the expression and the relationship of IL-38 and Treg Lymphocytes as well as periostin and activiated T lymphocytes in paediatric patients with asthma." (PMID 27438823, 2016). "Among these proteins, periostin is a member of the fascilin-1 family of proteins with known functions in wound repair, bone and teeth morphogenesis and remodeling, oncology, cardiovascular diseases, asthma and in several other inflammatory settings." (PMID 26809067, 2016). "This study sought to examine the ability of serum periostin to predict the presence of eosinophilic asthma and to determine the relationship between airway and serum periostin levels, inflammatory subtype and asthma control in a group of adults with poorly-controlled asthma." (PMID 27130294, 2016). "Both have been demonstrated to improve lung function and possibly reduce asthma exacerbations, but only in patients with severe asthma with biomarker evidence of a type-2 phenotype, demonstrated by elevated serum periostin levels or elevated IL-13 levels in sputum." (PMID 27942351, 2016). "However little is known about the airway levels of periostin and the relationships between airway periostin levels, asthma inflammatory subtypes and asthma control." (PMID 27130294, 2016). "This perplexing paradox may be explained by considering the heterogeneity of airway inflammation in asthma and the specific effects of periostin in mediating eosinophilic forms of asthma." (PMID 25981515, 2015). "The role of periostin in asthma and type 2 inflammatory responses is an area of active research." (PMID 25981515, 2015). "It is also hypothesized that pulmonary macrophage produce periostin through an autocrine function of periostin and this may contribute to the pathogenesis of asthma." (PMID 25981515, 2015). "It is possible that periostin may serve as a marker of cell classification and/or a therapeutic target for the treatment of asthma, and additional studies are needed to investigate these possibilities." (PMID 25981515, 2015).
asthma (continued). "This review will focus on what is known about periostin and its role in the pathophysiological mechanisms that mediate asthma in order to evaluate the potential for periostin to serve as a biomarker and therapeutic target for the detection and treatment of asthma, respectively." (PMID 25981515, 2015). "Therefore, it will be important to elucidate the role of periostin in the mechanisms that mediate the various asthma phenotypes." (PMID 25981515, 2015). "Periostin may also bind integrins α4 and β1/2, which have roles in mediating asthma, thereby triggering intracellular signaling pathways that repress mucus-inducing transcription factors such as NF-κB, Sp1, and AP-1." (PMID 25981515, 2015). "Indeed, expression of periostin in airway epithelial cell brushings strongly correlates with subepithelial fibrosis in asthma." (PMID 24146092, 2014). "Using microarray profiling of airway epithelial cells, we previously identified a Th2-high molecular phenotype of asthma based on expression of periostin, CLCA1 and serpinB2 and characterized by specific inflammatory, remodeling, and treatment response features." (PMID 23866775, 2013). "Mice lacking periostin respond to lung antigen challenge with significantly decreased number of eosinophils in the lung and have reduced allergic skin inflammation, thus implicating periostin as a ligand in eosinophil recruitment and retention in allergy and asthma." (PMID 23554594, 2013). "Periostin expression is increased in the airways of asthmatic subjects 2, 34, but its role in asthma pathogenesis is unknown." (PMID 22093101, 2012). "Periostin exhibits effects on epithelial cells and fibroblasts that may contribute to airway remodeling in asthma and may prove to be useful as a biomarker to identify those subjects most likely to give a positive clinical response to IL-13 antagonism." (PMID 23189057, 2012). "Though one might expect periostin to play a deleterious role in asthma pathogenesis, to date its biological role in the airway is unknown." (PMID 22093101, 2012). "The anti-IL-13 mAb lebrikizumab (Genentech/Chugai Pharmaceutical) has recently been demonstrated to significantly improve lung function in patients with inadequately controlled asthma, but only in a subgroup defined on the basis of high serum levels of periostin." (PMID 23189057, 2012). "Furthermore, serum periostin is an extracellular matrix protein released by airway epithelial cells stimulated with IL-13 that has potential as a biomarker of airway eosinophilia in patients with asthma." (PMID 41440490, 2025). "Additionally, periostin’s roles in other type 2-mediated disorders, including chronic rhinosinusitis and atopic dermatitis, open avenues for broader clinical application beyond asthma alone." (PMID 41374409, 2025). "Woodruff et al31 demonstrated that TH2-high and TH2-low asthma phenotypes, currently often referred to as type 2–high and type 2–low asthma phenotypes, can be differentiated on the basis of the expression levels of IL-13– and IL-13–inducible genes, including POSTN, which encodes periostin." (PMID 40687950, 2025). "Given that the novel periostin ELISA system, Assay B, can detect more periostin in sputum than the original periostin ELISA system, Assay A, we hypothesized that sputum from asthma patients contains the smaller-sized periostin product, most likely due to cleavage by a protease." (PMID 36763690, 2023). "However, according to a prospective cohort study, at the age of two years, periostin levels of ≥150 ng/mL could predict asthma at the age of six years." (PMID 37629446, 2023). "However, periostin’s usefulness in childhood asthma is still unclear." (PMID 37762787, 2023). "Moreover, periostin is a key driver of type-2 inflammation in asthma." (PMID 37241840, 2023).
asthma (continued). "Several biomarkers are available to phenotype asthma, some of which may predict clinical response to corticosteroids and T2 biologics; these include blood (or sputum) eosinophils, FeNO, serum total IgE (tIgE) levels, and periostin." (PMID 37035303, 2023). "In conclusion, inhibition of IL-4 and IL-13, and to a lesser degree inhibition of IL-13 alone, may benefit patients with T2 high asthma, such as those with elevated FeNO levels, elevated blood eosinophils (≥300 cells/μL) or sputum eosinophils (≥3%), and/or elevated periostin." (PMID 40980110, 2023). "The main goal of this study was to evaluate whether there is some association between the nasal detection and the levels of TSLP and periostin, in infants admitted for bronchiolitis, and the subsequent development of recurrent wheezing and asthma at 4 years of age." (PMID 36694181, 2023). "However, new studies continue to emerge describing a role for periostin in the pathogenesis of asthma, and serum periostin is also being used successfully in combination with other type two biomarkers such as blood eosinophils and FeNO to identify type-2 asthma." (PMID 36763690, 2023). "Dividing patients with asthma into those with eosinophilic and non-eosinophilic asthma based on the cut-off of 3% sputum eosinophils was associated with greater levels of serum and sputum periostin in the eosinophil-high group." (PMID 36763690, 2023). "However, other studies found similar serum periostin levels in children with severe asthma compared to those with controlled asthma or even lower periostin levels in children with severe uncontrolled asthma than in children with controlled asthma." (PMID 36694181, 2023). "However, lebrikizumab did not consistently show statistically significant reductions in asthma exacerbations in biomarker‐high adult patients (periostin ≥50 ng/ml, blood eosinophil count ≥300 cells/μl, or both); the primary endpoint was met in LAVOLTA I but not in LAVOLTA II." (PMID 35846226, 2022). "They found that asthma group and normal group had different transcriptomic profiles; in addition, genes such as pendrin and periostin were differentially expressed between asthma and normal, which might be relevant for the pathogenesis and treatment of disease." (PMID 34285702, 2021). "In addition to its role in respiratory diseases such as asthma and allergic pneumonia, it was found that plasma and SF POSTN levels were positively correlated with the radiographic severity of knee OA, and POSTN expression was increased in synoviocytes and SF from OA patients." (PMID 34513869, 2021). "Expression profiles reassembled in nasal and bronchial brushings, were specific to asthma independently of atopic status, and clustering analysis identified Th2-high and low subjects differentiated by expression of 70 genes (such as IL-13, IL-5, periostin, CLCA1, SERPINB2)." (PMID 32292784, 2020). "Periostin binds to several integrin molecules on the epithelial cell surface to support the adhesion and migration of epithelial cells, and elevated airway mucosal periostin may be useful in detecting type 2 CRSwNP and asthma." (PMID 33322143, 2020). "Compared with the severe OSA alone group (n = 41), the severe OSA with high periostin group (n = 12) exhibited significantly higher free fatty acid levels (p = 0.03) and prevalence of albuminuria (p = 0.04) and a trend for more frequent DM (p = 0.07) and asthma (p = 0.06)." (PMID 32517742, 2020). "High sputum TSLP levels may be induced by overexpressed periostin in the airway epithelium, but the specific mechanisms underlying the concurrent increase in local TSLP and periostin levels in asthma need further investigation in in vitro and in vivo experimental studies." (PMID 33203095, 2020).